TIPRL (TOR signaling pathway regulator)
Diseases named in the same sentence as TIPRL in open-access papers (continued):
Sharing a sentence is not in itself a finding about the gene and the disease.
cancer (11 papers, 2017 to 2025). A tumor composed of atypical neoplastic, often pleomorphic cells that invade other tissues. "TIPRL acts as a major player in stress-induced autophagy by directly interacting with eIF2α and inducing eIF2α phosphorylation, while TIPRL knockdown makes cancer cells more susceptible to environmental stress." (PMID 31862913, 2019). "TIPRL plays important roles in cell apoptosis and proliferation of cancer through the TIPRL/PP2A axis." (PMID 38383737, 2024). "Through ceRNA with miR-519d-5p, KCTD21-AS1 regulates the expression of CD47 and TIPRL, which further regulates macrophage phagocytosis and cancer cell autophagy." (PMID 38383737, 2024). "Regarding this pathway, we recently reported that TIPRL enhances cancer cell survival in metabolic and cellular stress via the induction of autophagic clearance." (PMID 34208132, 2021). "Despite this, little is known about the functional and prognostic implications of TIPRL in cancer, particularly in tumor metastasis." (PMID 32719745, 2020). "This action of TIPRL appears to protect cancer cells from TRAIL (tumor necrosis factor-related apoptosis-inducing ligand)—induced apoptosis." (PMID 32719745, 2020). "Another study showed that TIPRL potentiated mTORC1 signaling in human cancer cell lines, depending on amino acid availability." (PMID 31862913, 2019). "We found that knockdown of TIPRL led to the inhibition of cancer cell growth; this effect was partially reversed when co-transfected with HA-tagged TIPRL plasmid." (PMID 31862913, 2019). "In contrast, TIPRL ablation resulted in a substantial decrease of autophagy induction, which led to the reduction of cancer cell survival and enhanced cell death." (PMID 31862913, 2019). "Since TIPRL is reported to be closely related to the mTOR pathway, we employed Earle’s balanced salt solution (EBSS) as a starvation model to induce metabolic stress and elucidate the regulation mechanism of TIPRL on cancer cell growth." (PMID 31862913, 2019). "Cancerous tissues displayed an increase in both the mRNA and protein levels of TIPRL." (PMID 39076120, 2024). "Several studies have demonstrated the relationship between TIPRL and mTOR in cancer." (PMID 31862913, 2019). "Therefore, it is highly likely that cancer cells with elevated TIPRL expression levels exhibit a greater tendency to form malignant tumors." (PMID 31862913, 2019). "Our findings suggest that induction of metabolic and ER stresses coupled with the inhibition of autophagy by TIPRL ablation could be a highly selective and novel therapeutic approach for treatment of various types of cancer." (PMID 31862913, 2019). "Thus, TIPRL-regulated autophagy conferred a survival advantage to cancer cells by allowing them to respond quickly to hostile microenvironmental stresses." (PMID 31862913, 2019). "In addition, TIPRL overexpression and high levels of eIF2α phosphorylation were positively correlated with the malignancy of the cancer." (PMID 31862913, 2019). "TIPRL forms unusual wobble contacts with the PP2A scaffold subunit that underlie enhanced holoenzyme disassembly and inhibition of holoenzyme assembly of PP2A mutants that are linked to cancer and cause intellectual disability." (PMID 29273778, 2017). "The regulatory mechanism of TIPRL expression in cancer cells remains unknown." (PMID 39076120, 2024). "TIPRL’s wobble contacts with the scaffold subunit are unusual, unique among all known PP2A-interacting proteins, and suggest a mechanism wherein TIPRL can accommodate interactions with both wild-type and mutant PP2A implicated in cancer and neurological disorders." (PMID 29273778, 2017). "The roles of TIPRL/LC3/CD133/CD44/CD46 in liver normal and cancer cell lines were determined by in vitro studies." (PMID 34208132, 2021). "Thus, our findings may lead to further studies of the effects of TIPRL in other cancers." (PMID 32719745, 2020).
cancer (continued). "Previously, our group demonstrated that the TOR signaling pathway regulator-like (TIPRL) protein was upregulated in liver cancers, which resulted in the TRAIL resistance of cancer cells via de-phosphorylation of MKK713." (PMID 31862913, 2019). "We show that TIPRL upregulation in non-small cell lung cancer (NSCLC) potentiated autophagy activity and enabled autophagic clearance of metabolic and cellular stress, conferring a survival advantage to cancer cells." (PMID 31862913, 2019). "However, detailed and mechanistic studies of the potential role of TIPRL in cancer invasion and metastasis are not available." (PMID 32719745, 2020).
tumor (11 papers, 2017 to 2025). "TIPRL expression was shown to be lower in clinical GC tissues, and it was linked to a higher metastasis, tumor stage, and a worse clinical prognosis." (PMID 36212146, 2022). "Meanwhile, rescue experiments with Bcl2‐ and HMG20A‐expressing lentiviral particles were conducted to determine whether the decrease in tumor progression caused by TIPRL depletion was directly linked to the expression of Bcl2 and HMG20A in TIPRL‐depleted cells." (PMID 39076120, 2024). "Elevated CD47 inhibits macrophage phagocytosis of tumor cells, while higher TIPRL levels enhance tumor cell proliferation and survival." (PMID 40740874, 2025). "Conversely, as an inhibitor of PP2A, TIPRL modulates apoptosis-related signaling pathways to suppress apoptosis, thereby promoting tumor cell survival and proliferation." (PMID 40740874, 2025). "The survival rate was higher in mice that received TIPRL‐depleted cells versus controls, likely due to the decreased tumor frequency observed in the TIPRL‐depleted group." (PMID 39076120, 2024). "In the miR-383-5p/TIPRL pathway, the expression of TIPRL in GC tissues was related to the advanced tumor stage, more metastasis, and shorter survival times." (PMID 36313570, 2022). "As a result, TIPRL can protect tumor cells from TRAIL (tumor necrosis factor-related apoptosis-inducing ligand)-mediated apoptosis." (PMID 36313570, 2022). "Through hanging-drop culture, our results reveal that TIPRL knockdown inhibited spheroid formation of tumor cells exposed to microenvironmental stresses." (PMID 31862913, 2019). "Finally, immunohistochemistry was used to demonstrate that the TIPRL protein correlated with the strong signal observed in the adjacent tumor region stained with an anti‐CD133 antibody." (PMID 39076120, 2024). "Moreover, expression of hsa_circ_0010235 and TIPRL was downregulated, while miR-433-3p was upregulated in tumor tissues of sh-hsa_circ_0010235 group relative to those of sh-NC group." (PMID 33494763, 2021). "Overall, our data presents compelling evidence that TIPRL overexpression is closely related to tumor malignancy and that anticancer drugs accompanied by TIPRL ablation could be an effective approach to treatment." (PMID 31862913, 2019). "Additionally, immunostaining of CaMKK2 and TIPRL in a similar tumor region stained strongly." (PMID 39076120, 2024). "Three of the studies investigated reported on tumor tissue vs non-tumor tissue (GSE15471, GSE16515 and GSE101448), and in all these, we found an upregulation of KIAA1524/CIP2A, TIPRL, STRN and ARPP19, and a reduced expression of PPP2R1B in the tumor." (PMID 37170215, 2023). "Proteins encoded by PP2A genes identified to be highly correlating with aggressive PDAC in GSE62165 were also significantly different between normal tissue and PDAC tumor, with again CIP2A, TIPRL and STRN as top altered hits." (PMID 37170215, 2023). "TIPRL also promoted AMP-activated protein kinase (AMPK) activation, which in turn reduced phosphorylation of mTOR, 4EBP-1, and S6K, resulting in mTOR signaling deactivation and consequent inhibition of tumor invasion in GC." (PMID 36212146, 2022). "Moreover, TIPRL expression was markedly down-regulated in primary tumor samples with distant metastasis, compared to those without distant metastasis." (PMID 32719745, 2020).
infection (3 papers, 2015 to 2020). The state of being infected such as from the introduction of a foreign agent such as serum, vaccine, antigenic substance or organism. "Importantly, ERC1, CDC37, WDR61 and TIPRL showed similar reduction in protein levels during infection with the AD169 virus." (PMID 26599541, 2015).
TIPRL also shares sentences with these, for which no sentence is quoted: intrahepatic cholangiocarcinoma (2 papers); uterine cancer (2); carcinoid (1); developmental disabilities (1); gastrointestinal stromal tumor (1); Hepatic steatosis (1); intellectual disabilities (1); liver fibrosis (1); lung adenocarcinoma (1); lung squamous cell carcinoma (1); lymph node metastasis (1); melanoma (1); neurological disorders (1); prostate carcinoma (1); viral infections (1).